NPR2 (natriuretic peptide receptor 2)
Diseases named in the same sentence as NPR2 in open-access papers (continued):
Sharing a sentence is not in itself a finding about the gene and the disease.
Priapism (2 papers, 2014). A painful and harmful medical condition in which the erect penis doesn't return to its flaccid state, despite the absence of both physical and psychological stimulation, within four hours. "The rare Npr2slw/slw males that survive to adulthood exhibited unique and abnormal penile phenotypes, including paraphimosis and priapism; this unusual phenotype was also found in adult Npr2cn-2J/cn-2J and Npr2-KO mice (data not shown)." (PMID 25012822, 2014).
Short stature (2 papers, 2021 to 2025). A height below that which is expected according to age and gender norms. "Entire gene deletions and/or mutations causing loss of protein function in SHOX, IGF1R, NPPC, and NPR2 have been reported in familial short stature with various degrees of severity 18,37–40." (PMID 33850126, 2021). "This study reports two cases of familial short stature associated with heterozygous mutations in the NPR2 gene, which are linked to short stature with nonspecific clinical manifestations." (PMID 40750885, 2025).
aortic valve disease (1 paper, 2022). "Among these, a mouse model of premature aging (Klotho−/−) and heterozygote Npr2+/− and tissue-specific Sox9 mutants represents models in which genetic modification alone results in aortic valve disease." (PMID 36005436, 2022). "cGMP has been shown to mediate C-type natriuretic peptide/NPr2 signaling in valve interstitial cells, and defects in this signaling have been shown promote aortic valve disease in animal models." (PMID 36005436, 2022).
cardiomyopathy (1 paper, 2025). A disease of the heart muscle or myocardium proper. "Conversely, the downregulation of cardiomyopathy-related proteins (NPR2 and SLC25A11) aligns with blood-based findings of declining cardiac markers in aging, suggesting conserved cross-tissue aging mechanisms." (PMID 40662159, 2025). "Prominently downregulated proteins (TUBGCP2, NPR2, MT-ATP6, SLC25A11, and so on) were enriched in cytoskeletal dynamics and cardiomyopathy pathways, while upregulated proteins (ATP6V0D2, HNRNPA1, TPM1, and so on) associated with oxidative stress responses and neurodegenerative disorders (AD and PD)." (PMID 40662159, 2025).
CATSHL syndrome (1 paper, 2012). "Since the proband’s phenotype also showed similarity to CATSHL syndrome, caused by a loss-of-function mutation in the Fgfr3 gene, except for the absence of neurological symptoms, the Fgfr3 gene was analyzed as well as the natriuretic peptide precursor C (Nppc), Npr2, and Npr3 genes." (PMID 22870295, 2012).
colorectal cancer (1 paper, 2018). A primary or metastatic malignant neoplasm that affects the colon or rectum. "Despite its expression in normal tissues, over expression of NPR-2 is found in colorectal cancer cells and important for the development and metastasis of colorectal cancer cells." (PMID 29861465, 2018).
endometriosis (1 paper, 2025). The growth of functional endometrial tissue in anatomic sites outside the uterine body. "Additionally, we found that overactivation of the prolactin signaling pathway and the natriuretic peptide receptor 2 (NPR2) signaling pathway may promote the proliferation and migration of endometriotic cells, thereby exacerbating the condition of endometriosis." (PMID 40140093, 2025).
glioblastoma (1 paper, 2017). The most malignant astrocytic tumor (WHO grade IV). "We found that all the glioblastoma cell lines but A172 cell line expressed GUCY1A2, GUCY1A3, GUCY1B3, the subunits of the the dimeric soluble GC receptor activated by NO, as well as NPR2, the receptor-coupled GC isoform that binds C-type natriuretic peptide (CNP)." (PMID 28099939, 2017).
ileus (1 paper, 2021). Decrease in peristalsis in the absence of a mechanical bowel obstruction. "The Npr2 is a gene of NPR-B, and we previously reported a unique phenotype of a spontaneous mutant mouse lacking Npr2 (Npr2slw/slw), such as severe ileus-like disorder with bloodless blood vessels." (PMID 34838130, 2021).
intrauterine growth restriction (1 paper, 2022). "Among all the SGA children in our study cohort, 8.8% carried the NPR2 causal variant, highlighting possible prenatal causes of intrauterine growth restriction, especially within familial cases." (PMID 35741827, 2022).
Léri-Weill dyschondrosteosis (1 paper, 2022). "The penetrance of NPR2 heterozygous mutation was high, but the clinical presentation of patients was variable, and most of the patients showed short stature without skeletal dysplasia; however, patients with skeletal dysplasia similar to Léri-Weill dyschondrosteosis (LWD) were also observed." (PMID 35455946, 2022).
macrodactyly (1 paper, 2012). "Here we have described a three-generation family with tall stature and macrodactyly due to a newly identified gain-of-function mutation of the Npr2 gene, p.Val883Met." (PMID 22870295, 2012). "In conclusion, we have identified a gain-of-function mutation of Npr2 in a family with tall stature and macrodactyly." (PMID 22870295, 2012).
pituitary tumours (1 paper, 2021). "Our previous studies described the expression of NPPC and NPR2 in a range of human pituitary tumours, normal human pituitary, and normal fetal human pituitary." (PMID 33499110, 2021). "Similar to these models of rat pituitary tumours, we have previously shown that human somatotropinoma express both NPPC and NPR2." (PMID 33499110, 2021).
preeclampsia (1 paper, 2025). Preeclampsia is a hypertensive disorder of pregnancy that is characterized by new-onset hypertension with proteinuria presenting after 20 weeks of gestation, and depending on mild or severe forms may initially present with severe headache, visual disturbances, and hyperreflexia. "Lastly, our method only captures the potential effects of NPR2 and NPR3 on preeclampsia risk that are related to the same signaling pathways affecting height." (PMID 40406480, 2025). "Two-sample MR analyses were conducted to investigate the effects of NPR2 activation and NPR3 function on preeclampsia, utilizing the largest publicly available GWAS on preeclampsia, which included 296,824 female participants." (PMID 40406480, 2025).
prostate carcinoma (1 paper, 2013). A carcinoma that arises from epithelial cells of the prostate gland. "We also reported that the ability of VEGF/NPR2 to induce BMI-1 expression is FAK-dependent in prostate cancer." (PMID 23436775, 2013).
skeletal dysplasia (18 papers, 2013 to 2025). Any Mendelian diseases that affects growth and development of the skeleton. "A notable aspect of this study was the frequency of heterozygous mutations detected in genes previously associated with skeletal dysplasia (NPR2, ACAN, CASR, COMP, and FBN1), confirming the dose effect of cartilage matrix proteins in growth and development." (PMID 37605180, 2023). "Previous studies showed that NPR2 gene variants can manifest as isolated short stature or in conjunction with skeletal dysplasia." (PMID 35455946, 2022). "Recessive inactivating mutations or knockout in Npr2 gene results in growth insufficiency, skeletal dysplasia in mice and rats associated with small proliferative and hypertrophic chondrocyte areas." (PMID 35455946, 2022). "Numerous loss-of-function mutations have now been reported in NPPC and NPR2, leading to profound skeletal dysplasias and short stature." (PMID 33499110, 2021). "NPR2 mutations may affect the natriuretic peptide signaling pathway, disrupting the regulation of bone growth and ossification, leading to skeletal dysplasia characterized by abnormal bone development and ossification." (PMID 40462134, 2025). "We further investigated their function, expression, and subcellular abnormal localization of the mutant NPR2 protein and studied the differentiation and apoptosis of chondrocytes to explore the potential pathogenesis of NPR2 gene mutation resulting in skeletal dysplasia." (PMID 35455946, 2022). "Genetic disorders associated with skeletal dysplasia include many genes involved in growth plate development, such as FGFR3, ACAN, NPR2, FBN1, and IHH, which can cause varying degrees of short stature with or without other minor abnormalities." (PMID 35250876, 2022). "The diverse phenotypes of the mice expressing the gain-of-function mutant Npr2 resemble various conditions of bovine skeletal dysplasia." (PMID 26306008, 2015). "All three patients with NPR2 (p.R318W, p.I908T, p.R976H) gene mutations exhibited non-specific skeletal dysplasia and short stature, with good efficacy of recombinant human growth hormone (rhGH) treatment." (PMID 40750885, 2025). "The penetrance of NPR2 heterozygous mutations is high, but there is significant variability in clinical manifestations among patients, with the majority exhibiting short stature without skeletal dysplasia." (PMID 40750885, 2025). "In addition, for the general short-stature population with skeletal dysplasia, ACAN-related short stature was more responsive to rhGH treatment than NPR2-related short stature, and significant height improvement was not seen in FGFR3-related short-stature patients in this cohort." (PMID 35250876, 2022).
tumor (7 papers, 2010 to 2025). "The tumor volumes were measured 36 mm3 and 420 mm3 for both NPR-2-siRNA-DOPC- and control siRNA-DOPC-treated mice." (PMID 29861465, 2018). "Liposomal complexes of NRP-2-targeted siRNA (NPR-2-siRNA-DOPC) could be used to slow down the tumor growth." (PMID 29861465, 2018). "Tumor growth was clearly slowed down by NPR-2-siRNA-DOPC (91.43%) compared to control siRNA-DOPC." (PMID 29861465, 2018). "Resistance to cisplatin has been initially observed in yeast S. cerevisiae for Npr2 and Npr3 deletion mutants (NPRL2 and NPRL3 homologs, respectively), years before GATOR1 components were suggested to be tumor suppressors." (PMID 41469472, 2025). "NPRL2 (human ortholog of NPR2) and DEPDC5 (human ortholog of IML1) have been reported to function as tumor suppressors." (PMID 23705068, 2013).
cancer (3 papers, 2020 to 2025). A tumor composed of atypical neoplastic, often pleomorphic cells that invade other tissues. "Based on the density of local network regions, we predicted CHMP7, NPR2, and TUBB6 as novel pathogenic genes whose splice variants impact the interaction network similarly as splice variants of cancer-associated genes." (PMID 32879328, 2020). "We hypothesized that radiotherapy enriches for NPR2-expressing cancer cells within tumors; thus, we screened several TNBC-derived cell lines and observed a positive correlation between radiation dosage and NRP2 cell-surface expression." (PMID 39352757, 2024). "Given that the chromosome structure is often altered in cancer, the cMDT of NPR2 could hint towards a role of NPR2 in cancer." (PMID 32879328, 2020).
infection (3 papers, 2016 to 2021). The state of being infected such as from the introduction of a foreign agent such as serum, vaccine, antigenic substance or organism. "The DEA of NPR proteins indicated that 4 PM-responsive and 4 DM-responsive NPR (comprised of NPR1 and NPR2) genes were expressed differentially during infection and all NPR genes were shown to be steadily up-regulated from initial to later stages of both powdery and downy mildew infection." (PMID 34717533, 2021). "At 1 dpi of DM infection, the relative expression levels of NLR, NDR1, EDS1, NPR2 and TGA TFs coding genes was higher as compared to control." (PMID 34717533, 2021).
genetic disorders (2 papers, 2020 to 2023). "This study enhances our understanding of the functional consequences of several NPR2 variants, shedding light on their mechanisms and roles in related genetic disorders which might also help in their pathogenicity re-classification." (PMID 38078000, 2023). "Various human genetic disorders have been linked to genetic variations in NPR2 gene." (PMID 38078000, 2023).
cardiac diseases (1 paper, 2023). "Examples of drug targets for cardiac diseases detected in primary cardiac fibroblasts but not in hPSC-CFs include AOC3 (hydralazine) and NPR2 (nesiritide)." (PMID 36950336, 2023).
NPR2 also shares sentences with these, for which no sentence is quoted: cardiovascular diseases (3 papers); Myocardial fibrosis (3); hypochondroplasia (2); myocardial infarction (2); short-limb dwarfism (2); 22q11.2 deletion syndrome (1); amyotrophic lateral sclerosis (1); Anxiety (1); arachnodactyly (1); Arrhythmia (1); asthenospermia (1); atherosclerosis (1); atrial fibrillation (1); autonomic dysfunction (1); Co-infection (1); congenital adrenal hyperplasia (1); congestive heart failure (1); Crouzon syndrome (1); diabetes mellitus (1); embryonic carcinomas (1); esophageal cancer (1); Hyperglycemia (1); Hyperinsulinemia (1); hyperthyroidism (1); Klinefelter syndrome (1); left ventricular hypertrophy (1); medulloblastoma (1); melanoma (1); nephrotic syndrome (1); osteoarthritis (1).
A further 9 diseases each share a sentence with NPR2 in 1 paper.